DAXX (death domain associated protein)
Diseases named in the same sentence as DAXX in open-access papers (continued):
Sharing a sentence is not in itself a finding about the gene and the disease.
cancer (94 papers, 2012 to 2025). A tumor composed of atypical neoplastic, often pleomorphic cells that invade other tissues. "Among the biomolecules implicated in cancer epigenetics, DAXX, HJURP and CENPA represent three proteins heavily impacting oncogenesis in a variety of tumors." (PMID 39200236, 2024). "Previous studies have identified a common denominator of interest in various cancers, namely that DAXX is overexpressed in a variety of cancers and its possible association with tumorigenesis, disease progression, and treatment resistance." (PMID 35222097, 2022). "Inactivation of ATRX, or, less frequently, its associated protein DAXX, through deleterious mutations, has been increasingly observed in subsets of cancers, and is consistently associated with ALT." (PMID 35740680, 2022). "DAXX mediates the ectopic deposition of CENP-A in cancers where this centromeric histone variant is overexpressed." (PMID 34830833, 2021). "The functions of ATRX and DAXX in the chromatin landscape, as well as the functional modules they harbor, and the mutations/alterations observed in cancer have been reviewed recently." (PMID 34830833, 2021). "Sequencing of cancer genomes discovered that mutations of the ATRX/DAXX complex and the histone variant H3.3 are prevalent in ALT+ cancers." (PMID 32175073, 2020). "Loss of ATRX or DAXX though mutation has been reported in cancers which are histogenetically remote from OC." (PMID 32533344, 2020). "Although genetic mutations in ATRX and DAXX are often demonstrated in ALT positive cancers, a fraction of cancers display significant defects in DAXX/ATRX protein expression and/or function that do not stem from genetic mutations." (PMID 30214690, 2018). "First, CENP-A, which is innately overexpressed in cancer cells, associates with histone H3, and shows increased association with transcription-coupled chaperones DAXX and ATRX." (PMID 25788983, 2015). "Another common association in ALT-positive cancer genomes that may be related to T-SCE is mutations in the ATRX/DAXX complex." (PMID 39858038, 2025). "Similarly, HIRA can compensate for the loss of DAXX/ATRX by depositing H3.3 onto telomeric heterochromatin in alternative lengthening of telomeres (ALT) cancer cells." (PMID 38297159, 2024). "Death domain-associated protein (Daxx) binds E-boxes to antagonize the trans-suppressive effect of Slug on E-cadherin, subsequently stabilizing E-cadherin expression and suppressing cancer cell invasion and metastasis during hypoxia." (PMID 33691694, 2021). "There is growing recent evidence that mutations in the DAXX gene may be associated with some cancers, suggesting DAXX as one of the most important factors in maintaining the integrity of the genome." (PMID 33525665, 2021). "Nonetheless, DAXX is rarely mutated in commonly diagnosed cancer types." (PMID 31350900, 2019). "Depletion of the histone chaperone protein ASF1 is able to induce the ALT mechanism concomitant with inhibition of telomerase activity in HeLa cells; moreover (as reported in Section 2.1) mutations in genes encoding for the ATRX/DAXX complex have been found in many ALT cancers." (PMID 29463031, 2018). "Additionally, multiple reports have demonstrated that ATRX mutation or loss of expression results in ALT and genomic instability, and many ALT cancers harbor mutations in ATRX or DAXX genes encoding proteins that interact with each other at telomeres." (PMID 24810474, 2014). "Menin, DAXX, and ATRX are therefore key proteins involved in the maintenance of gene transcription, and therefore their loss of function is associated with many cancer types for example leukaemia, prostate cancer, gliomas, and sarcomas." (PMID 39579056, 2025). "A loss of DAXX and/or ATRX expression has been associated with activation of alternative lengthening of telomeres (ALT), a mechanism that enables cancer cells to maintain telomere length and sustain proliferation." (PMID 41472189, 2025).
cancer (continued). "Accordingly, dysregulation of HIRA or DAXX complexes is observed in various types of cancers, such as breast, lung, prostate, colorectal, glioma, pancreatic, leukemia, prostate, gastric, ovarian, and chondrosarcoma." (PMID 38297159, 2024). "Recent advances in cancer genome sequencing have revealed somatic mutations in ATRX and DAXX, which seem to be prevalent and unique to ALT-positive malignancies." (PMID 39021990, 2024). "Loss of ATRX and DAXX can also be found in telomerase positive cancers, albeit with low frequency, and some ALT phenotypes have been observed in telomerase-positive cancer lines that have acquired ATRX mutations." (PMID 36805596, 2023). "For instance, shared clonal mutations in driver genes such as ATM, ATRX, BRCA1/2, DAXX, MSH3, and MSH6 are associated with aberrations in major cellular signaling pathways like Pathways in cancer, DNA damage response, and regulation of cell cycle." (PMID 36140756, 2022). "The tumor suppressor proteins DAXX and ATRX are frequently mutated in cancers with alternative lengthening of telomeres (ALT)." (PMID 36028493, 2022). "Previous studies have found a noteworthy commonality among various cancers in that DAXX is overexpressed in a variety of cancers and its possible association with tumorigenesis, disease progression and treatment resistance." (PMID 35222097, 2022). "As transcriptional factor coregulator involved in cell proliferation and apoptosis, the role of ATRX/DAXX in cancer development is controversial." (PMID 36428674, 2022). "Nonsynonymous mutations were also identified in 51 additional cancer genes in single primary ileal NETs and metastases, including ALK, DAXX, KRAS, and MEN1." (PMID 35922826, 2022). "DAXX and ATRX are tumor suppressor proteins that form a histone H3.3 chaperone complex and are frequently mutated in cancers with the alternative lengthening of telomeres (ALT)." (PMID 36028493, 2022). "DAXX is a transcription repressor involved in the regulation of cell proliferation, apoptosis and the development of cancer." (PMID 32203224, 2020). "DAXX and/or ATRX expression has been associated with both better and worse survival in analysis of other cancers." (PMID 32533344, 2020). "Other studies suggested that DAXX is dysregulated and involved in pivotal events in the progression of several cancers." (PMID 31942198, 2020). "The synthetic circular miR-21 (scRNA21) sponge inhibited cancer cell proliferation and suppressed the activity of miR-21 on downstream protein targets, including the cancer protein DAXX." (PMID 32213977, 2020). "We also investigated the molecular mechanisms by which DAXX downregulation promotes cancer growth using both in vitro and in vivo models." (PMID 32203224, 2020). "To extend our data to humans, we characterized the expression of MYCN, ATRX, and DAXX proteins across 12 human cancer cell lines." (PMID 32060267, 2020). "For instance, in some types of cancer, DAXX can act as a transcriptional co-repressor to inhibit oncogene expression or promote Fas-mediated cell death." (PMID 32641734, 2020). "Remarkably, DAXX overexpression is a common feature in diverse cancers, which correlates with tumorigenesis, disease progression and treatment resistance." (PMID 31350900, 2019). "DAXX downregulation in human cancer cells sensitizes cells to apoptosis through the activation of JNK and caspases." (PMID 31350900, 2019). "In details, increased DAXX expression has been consistently observed in diverse epidemiologically prevalent cancer types." (PMID 31350900, 2019). "Taken together, these findings support DAXX upregulation as a prognostic marker for carcinoma progression." (PMID 31614769, 2019).
cancer (continued). "The identification of genetic mutations in ATRX, DAXX, H3.3, and more recently SMARCAL1 in ALT positive cancers has been instrumental in further defining the molecular basis of ALT." (PMID 30214690, 2018). "A striking correlation has been observed between ALT activity in various human cancers and loss of the ATP-dependent helicase ATRX or its binding partner, the H3.3-specific histone chaperone DAXX, both of which are constituents of PML bodies." (PMID 29848986, 2018). "As an alternative to upregulation of TERT expression, cancers can also use the ALT pathway for telomere maintenance, associated with inactivating mutations in either the ATRX or DAXX genes." (PMID 29312603, 2017). "Our results showing that DAXX depletion rescues CENP-A overexpression induced chromosome missegregation provide an exciting avenue for DAXX as a biomarker for CENP-A overexpressing cancers." (PMID 28596481, 2017). "In our study, using overexpression of TPP1ΔOBRD and double knocking down ATRX and DAXX by shRNAs, we observed APBs and C-circles increasing during the switch from telomerase-positive cancer cells to ALT-like cells." (PMID 27578458, 2016). "In summary, this is the first report to show that inducing telomeric DNA damage, disrupting the ATRX/DAXX complex and inhibiting telomerase activity in telomerase-positive cancer cells lead to the ALT switch." (PMID 27578458, 2016). "How does ATRX/DAXX repress ALT and what is the molecular basis of its activation in cancer cells with wild-type ATRX/DAXX?" (PMID 27323951, 2016). "We assessed transcription-coupled histone chaperones ATRX and DAXX, and observed that both are overexpressed in most cancer cell lines relative to normal colon, ranging from three- to twentyfold excess protein." (PMID 25788983, 2015). "Mutations in the ATRX/DAXX complex and histone H3.3 were found to correlate with features of ALT in many cancers." (PMID 24563217, 2014). "An even greater interest in H3.3 and its chaperones has arisen from the discovery that H3.3 itself, DAXX and ATRX are mutated in human cancer." (PMID 23760585, 2013). "At present, it is unclear what are the expression levels of the H3.3 chaperones HIRA and DEK in pancreatic tumors and other cancers displaying alterations in H3.3 and DAXX/ATRX loading machinery." (PMID 23760585, 2013). "The involvement of factors like RAD51 and the ATRX/DAXX complex suggests that further elaboration of this pathway could provide critical insights into how ALT-positive cancers maintain their proliferative capacity." (PMID 39858038, 2025). "Furthermore, DAXX functions as an anaphase-promoting complex (APC) inhibitor, promoting chromosome instability and cancer predisposition during prostate cancer development." (PMID 38297159, 2024). "We also identified alterations in genes involved in various critical biological processes: MDC1, associated with DNA damage response and drug resistance in MM; DAXX, involved in chromatin regulation; GPNMB, linked to immunosuppression in cancer; and XK, which plays a role in hematopoiesis." (PMID 39769182, 2024). "Almost all ALT+ cancer cells exhibit loss of the ATRX gene and/or its interaction partner DAXX, however, the precise role of ATRX/DAXX loss in the initiation and maintenance of ALT remains unclear." (PMID 36940725, 2023). "About 16% of cancers in the Pan-Cancer Analysis of Whole Genomes (PCAWG) dataset were found to harbor somatic mutations in at least one of these three genes (TERT, ATRX, and DAXX) involved in telomere maintenance." (PMID 37761808, 2023).
cancer (continued). "Sequencing data from the Sanger and Broad Institutes indicated that none of these cancer cell lines displayed a mutation in ATRX or DAXX, except NOS1 that had a homozygous loss of the ATRX genes." (PMID 35920001, 2022). "Further, a subset of cancers shows extremely low TERT expression, possibly suggesting they belong to ALT through mutations outside ATRX or DAXX or to completely unknown telomere maintenance pathways." (PMID 34097189, 2021). "Interestingly, DAXX overexpression in cancer is related to disease progression and treatment resistance." (PMID 34680332, 2021). "Dysregulation of DAXX is strongly correlated with cancer metastasis." (PMID 31942198, 2020). "The role of DAXX in the development of cancer remains controversial." (PMID 32203224, 2020). "We found that knockdown of DAXX was sufficient to promote cancer migration and invasion in vitro." (PMID 31942198, 2020). "While our study requires further validation, our results suggest that reagents targeting the DAXX/ZEB1 pathway could help decrease cancer cell motility and invasiveness and thus prevent metastasis in CRC." (PMID 31942198, 2020). "Mutations in ATRX, DAXX, and H3.3 are prevalent in ALT+ cancers." (PMID 32175073, 2020). "Importantly, DAXX is also upregulated in some cancer cell lines where CENP-A is upregulated, and both DAXX and HJURP have structurally similar histone binding domains." (PMID 32708729, 2020). "The frequency of tumors lacking detectable hTERT expression and mutations of ATRX/DAXX reached up to 70–80% in some cancer types like thyroid carcinoma (79.1%), kidney renal papillary cell carcinoma (70.2%), kidney cromophobe carcinoma (80%)." (PMID 29463031, 2018). "Here, we show that cancers with somatic mutation of SMARCAL1 are ALT positive, and this represents, to our knowledge, the only other reported gene mutation associated with ALT other than ATRX and DAXX mutations." (PMID 29802247, 2018). "It is unclear how these mutations are driving cancer in young patients, but it is likely that ATRX and DAXX deficiencies have adverse effects on chromatin structure that may contribute to the development of cancer." (PMID 29479426, 2018). "Our results contribute to a growing body of literature that is revealing ATRX-independent functions of DAXX that may have important implications for viral restriction, cancer biology, and epigenetics." (PMID 30465651, 2018). "Telomerase-independent cancers maintain their telomeres through a homologous recombination-dependent process known as alternative lengthening of telomeres (ALT), which is associated with genomic alterations in the genes DAXX or ATRX." (PMID 29312603, 2017). "It has recently been shown that ATRX mutations or the absence of ATRX protein is an almost invariant finding in cell lines exhibiting the ALT phenotype and that various cancers with features consistent with the ALT phenotype are frequently associated with mutations in ATRX, DAXX and/or H3.3." (PMID 24651726, 2014). "DAXX (Death Domain-Associated Protein), HJURP (Holliday Junction Recognition Protein) and CENPA (Centromere Protein A) proteins are implicated in epigenetic mechanisms, now in the spotlight of cancer research to better understand the molecular background of tumorigenesis." (PMID 39200236, 2024). "In a previous study, 22% of all TCGA cancers did not express TERT or had mutations in ATRX or DAXX." (PMID 34681758, 2021). "DAXX/ZEB-1 pathway could be a potential therapeutic target for preventing cancer metastasis in CRC." (PMID 31942198, 2020). "Importantly, the compelling evidence that DAXX has an oncogenic function as reviewed here suggests that targeting of DAXX-mediated mechanisms could have therapeutic potential for treating different cancer types." (PMID 31350900, 2019).
cancer (continued). "Genetic mutations in ATRX, DAXX, and H3.3 have been detected in ALT positive cancers, however, a subset of ALT samples show loss of ATRX or DAXX protein expression or localization without evidence of genetic alterations suggesting additional uncharacterized defects in ATRX/DAXX/H3.3 function." (PMID 30214690, 2018). "However, it does suggest that the DAXX gene locus is susceptible to genetic rearrangements and that these rearrangements have the potential to drive cellular immortality through ALT in these cancers." (PMID 30214690, 2018). "In this study, we used telomerase-positive cancer cells (HTC75) to discover the mechanism of the telomerase-ALT switch by inducing telomere-specific DNA damage, alpha-thalassemia X-linked syndrome protein (ATRX) knockdown and deletion of death associated protein (DAXX)." (PMID 27578458, 2016). "One of the reasons might due to telomerase-positive cancer cells have functional ATRX/DAXX complex." (PMID 27578458, 2016). "A number of lines of evidence indicate that in a cancer context, like in development (Daxx-null genotype is an embryonic lethal condition in which the embryos die by age E9.5, due to global apoptosis), DAXX may have a pro-survival role." (PMID 26097870, 2015). "This study aims to investigate alterations in the epithelial nuclear expression levels of DAXX and ATRX in canine carcinomas of the prostate and bladder using immunohistochemical methods combined with AI-assisted digital image analysis." (PMID 41472189, 2025). "Since epithelial nuclear expression was considered more relevant for assessing alterations of DAXX and ATRX in carcinomas, variations in stromal expression and inflammatory cells were not further analysed." (PMID 41472189, 2025). "We also found that other known cancer-related genes were also altered at low frequency including APC (n = 5), KRAS (n = 2), SETD2 (n = 2), DAXX (n = 1) and STAG2 (n = 1)." (PMID 37524847, 2023). "DAXX can be modified by SUMO1 increasing recruitment of DAXX to PML-NBs, which induces cancer cell apoptosis." (PMID 36911524, 2023). "Therefore, ATRX and DAXX may promote or inhibit malignant neoplasms, depending on the cancer type." (PMID 36428674, 2022). "HS-dependent deposition of DAXX, a PML client, at peri-centromeric heterochromatin was detected, while DAXX was sequestrated in PML-NBs in normal conditions in cancer cell lines." (PMID 35579421, 2022). "The pan-cancer PCAWG dataset had a similar pattern as the FMI dataset, where both the ATRX/DAXX and RAD21 altered groups had higher telomeric content compared to WT samples." (PMID 35227290, 2022). "Given the critical roles for DAXX, E-cadherin, and the ZEB proteins in cancer development and metastasis, we sought to investigate how DAXX regulates E-cadherin in the metastasis of CRC and how the ZEB proteins are involved in the process." (PMID 31942198, 2020). "To better understand the mechanism that leads to the telomerase-ALT switch in telomerase-positive cancer cells, we constructed different cell lines with specific telomeric DNA damage, ATRX knockdown, DAXX deletion or TERT KO." (PMID 27578458, 2016). "DAXX and ATRX form the histone 3.3 (H3.3) chaperone complex, which loads H3.3 into the telomeric region of the chromatin that protects the DNA from alternate lengthening of telomers, a mechanism commonly used by cancer cells." (PMID 39579056, 2025). "Our results indicated that DAXX and ATRX undergo coordinated expression changes during malignant transformation, consistent with their known role as functional partners in chromatin regulation and telomere maintenance in human cancers." (PMID 41472189, 2025). "In previous works, we and others reported that CENP-A accumulates at non-centromeric sites in cancer cells, and that this non-native pathway exploits the H3.3 chaperone, DAXX." (PMID 38825690, 2024).